AR (androgen receptor)
Diseases named in the same sentence as AR in open-access papers (continued):
Sharing a sentence is not in itself a finding about the gene and the disease.
prostate carcinoma (continued). "Of the long noncoding RNAs involved in prostate carcinogenesis, PCGEM1 and PRNCR1 (prostate cancer noncoding RNA1) have been identified as playing critical roles via coordination with AR." (PMID 26110379, 2015). "The aim of these studies was to reveal differential regulation of androgen receptor expression and activity in an isogenic pair of prostate cancer cells that serve as models for progression to castration resistance." (PMID 26154658, 2015). "DJ-1 has been previously shown to increase AR activity by abrogating binding of the inhibitory histone deacetylase complex and expression is up-regulated in several cancers, including prostate cancer." (PMID 25693800, 2015). "KDM3A removes transcriptionally repressive mono- and di-methyl marks from H3K9 and has been shown to be required for successful AR recruitment to AR-target gene promoters in prostate cancer cell lines upon ligand stimulation." (PMID 25488809, 2015). "Castration and androgen receptor (AR) pathway inhibitors induce profound and sustained responses in advanced prostate cancer." (PMID 25896606, 2015). "Our work demonstrates the negative regulation of AR/miR-101 on celastrol-induced autophagy in AR positive prostate cancer cells." (PMID 26473737, 2015). "Prostate cancer (PCa) is the most commonly-diagnosed malignancy in men, and is driven by androgen hormones acting via their cognate nuclear androgen receptor (AR) transcription factor." (PMID 25592066, 2015). "Prostate cancer cells rely uniquely on androgens for proliferation, and blocking the AR pathway with androgen deprivation therapy invariably induces tumor regression." (PMID 26110379, 2015). "The androgen receptor (AR) and its signaling pathway play an important role in the development and progression of prostate cancer (PCa)." (PMID 25793207, 2015). "Prostate cancer (PCa) onset and progression is driven by androgen steroid hormones binding to their cognate androgen receptor (AR) nuclear hormone receptor transcription factor." (PMID 26310125, 2015). "Accumulative evidence suggests that castration-resistant activation of androgen receptor (AR) and development of apoptosis-resistant cells play key roles in the transition of androgen-dependent prostate cancer to CR prostate cancer." (PMID 26622945, 2015). "In prostate cancer, free β-catenin regulates AR as a result of activation of wingless (Wnt) signaling pathways, and activation of the phosphoinositide 3-kinase (PI3K)/protein kinase B (Akt) pathway is thought to be an upstream regulator of this event." (PMID 26207810, 2015). "Of note, HES6 has been recently reported to play an important functional role in prostate cancer enhancing oncogenic signalling through the AR." (PMID 25560400, 2015). "The recent wave of novel anti-androgen agents, as abiraterone and enzalutamide, serves as proof-of-principle that AR signaling continues even in the so-called castration-resistant prostate cancer population." (PMID 25595907, 2015). "Since AR is instrumental in the progression of prostate cancer (PC), it has been the main focus of therapeutics." (PMID 25965834, 2015). "These represented cell cycle/mitosis; among others CCNE1, CCNE2, CCNG2, CCNL1, CCNT1, CDK12 and CDKN3, prostate cancer; including the androgen receptor (AR), metabolism as well as targets of the transcription factors E2F, AP2, SP1, ETF and Pax3." (PMID 26698305, 2015). "AR is generally considered as the main driver in prostate cancer tumorigenesis and tumor progression." (PMID 26412853, 2015). "Considering that ER-β is a molecular antagonist of AR, this study linked the interaction of BPA with ER and AR to shed light on the mechanisms of the cell proliferation-promoting effects of BPA in prostate cancer cells." (PMID 25569640, 2015). "On the other hand, although the AR remains the major target for prostate cancer prevention and treatment, ER is also involved in prostate cancer development and tumour progression." (PMID 25693204, 2015).
prostate carcinoma (continued). "The stress response that is activated by castration in AR-driven prostate cancers includes up-regulation of molecular chaperones that regulate protein homeostasis and diverse survival signalling and transcriptional survival networks." (PMID 25896606, 2015). "Given the important role of the androgen receptor (AR) in prostate cancer, AR-targeted therapies are the backbone of therapy for almost all patients and no specific genetic test is warranted." (PMID 26258074, 2015). "The binding of androgens to the androgen receptor (AR) plays an important role not only in the growth and development of normal prostate, but also in prostatic diseases including prostate cancer (PCA)." (PMID 25816367, 2015). "The results of our study identify HOXB13 overexpression as a strong prognostic factor in prostate cancer, and suggest clinically relevant in-vivo interactions with its binding partner androgen receptor." (PMID 25825985, 2015). "Androgens drive the onset and progression of prostate cancer (PCa) via androgen receptor (AR) signalling." (PMID 25592066, 2015). "Even in its late stages, AR signaling remains an important driver of prostate cancer progression, with most of the adaptive changes that occur within a prostate cancer cell stemming from a persistent addiction to the AR." (PMID 26566796, 2015). "There is a high correlation between AR expression and response to hormonal treatment, and anti-androgens are therefore the mainstay of therapy for patients with prostate cancer [S59, S60]." (PMID 25595907, 2015). "The AR represents perhaps the first described lineage-specific oncogene, with prostate cancer demonstrating a persistent addiction to AR- ignaling even in its late stages—a reflection of its emergence from normal prostatic epithelium." (PMID 26566796, 2015). "Most prostate cancer cells express the androgen receptor (AR) and are dependent on AR action for growth and proliferation." (PMID 26372468, 2015). "Many of the patients who develop prostate cancer receive AR antagonists, to inhibit the actions of androgens on proliferation of prostate epithelia." (PMID 26008968, 2015). "Other evidences for the role of SENP1 in prostate cancer tumorigenesis include the increase in androgen receptor activity and c-Jun dependent transcription." (PMID 25893082, 2015). "In the cell lines derived from pancreatic adenocarcinoma, AR+ prostatic carcinoma, osteosarcoma, and colon cancer, TRPM8 is required for sustaining cellular proliferation." (PMID 26512697, 2015). "Reflective of the reliance of prostate cancer on the expression of AR target genes is the observation that over 70 % of CRPC cases harbor AR pathway aberrations, with AR transcriptional activity persisting in the majority of cases of CRPC." (PMID 26566796, 2015). "Analysis of the abundance of miR-190a and AR by Taqman quantitative real-time PCR (qRT-PCR) in prostate cancer specimens showed a significant decrease of miR-190a levels in prostate cancer tissues (n = 40) when compared to normal prostate tissue (n = 20)." (PMID 26314494, 2015). "Our data reveals that TCDD effect on AR expression and activity differs in androgen sensitive LNCaP and castration-resistant C4-2 prostate cancer cells." (PMID 26154658, 2015). "PAK6 has been reported to be an important tumor suppressor in prostate cancer cells based on its ability to phosphorylate the androgen receptor, tumorigenic E3 ligase murine double minute-2 (Mdm2), and β-catenin." (PMID 25714010, 2015). "The up-regulation of CDKN1A mRNA is also consistent with AR-mediated transcriptional activation, which has been reported previously in prostate cancer-derived cell lines." (PMID 26372468, 2015). "Investigations have shown that ligand-independent activation of the AR pathway occurs in prostate cancer, which can be enhanced by epidermal growth factor (EGF) through the signal transduction pathway." (PMID 26347776, 2015).
prostate carcinoma (continued). "The persistence of androgen receptor (AR) signalling in castrate-resistant prostate cancer (CRPC) highlights the unmet clinical need for the development of more effective AR targeting therapies." (PMID 26267320, 2015). "For example, cells that lack AR expression or had repressed AR signaling have been reported in large numbers of metastatic tumors derived from prostate cancer patients." (PMID 25537508, 2015). "Our in vivo analysis suggests that the relative expression of AR isoforms can persist during CRPC and prompted us to examine the implications of a relative increase in expression of mAR-Vs in Pten deficient prostate cancer." (PMID 26196517, 2015). "The AR clearly represents the Achilles’ heel of prostate cancer yet the current primary treatment involving androgen antagonists has limitations and also leads to expression of an alternative AR-driven transcriptome with variable PCa outcomes." (PMID 26448047, 2015). "One of the more commonly observed events as prostate cancer progresses from a hormone-sensitive to castration-resistant state is the adaptive upregulation of the AR, a finding supported by preclinical as well as clinical studies." (PMID 26566796, 2015). "Mining of three prostate cancer cell ChIP-Seq datasets revealed region D1, encoding an ARE sequence motif, to be bound by AR specifically upon DHT treatment." (PMID 26559958, 2015). "Here, we found the CCL5 secreted from BM-MSCs suppressed androgen receptor (AR) signals via enhancing the expression of hypoxia inducible factor 2α (HIF2α) in prostate cancer (PCa) cells." (PMID 26342197, 2015). "The androgen receptor (AR) is a driver of prostate cancer (PCa) cell growth and disease progression." (PMID 25669987, 2015). "Prostate cancer is, in its early stages, an AR‐dependent malignancy and non‐curative treatments, such as anti‐androgens, are designed to inhibit AR signalling." (PMID 25241147, 2015). "We previously demonstrated that AR activation in prostate cancer cells increases integrin α6β1 transcription and expression." (PMID 25730905, 2015). "We showed that curcumin inhibited the growth of androgen-independent prostate cancer cells and a synergy was observed in the presence of curcumin and bicalutamide, the androgen receptor antagonist." (PMID 25971429, 2015). "Other studies have determined the responses of prostate cancer cells to various ligands of the AR and it has been demonstrated that ligand-specific gene regulation by the AR can occur (11, –13)." (PMID 25693800, 2015). "Sequencing-based genomic abnormality analysis revealed locus-specific gains or losses that were common in prostate cancer, such as 8q gains, AR amplifications, PTEN losses and TMPRSS2-ERG fusions." (PMID 25915538, 2015). "Our findings provide the first preclinical evidence that simultaneous inhibition of AR and eIF4E activation is a novel and efficacious therapeutic approach for PCa, and that NRs hold significant promise for treatment of advanced prostate cancer." (PMID 25605250, 2015). "Pathway mapping of the two gene sets supported the importance of the androgen receptor-mediated signaling in prostate cancer biology." (PMID 25658610, 2015). "Our understanding for how prostate cancers are able to progress in spite of drugs that should effectively prevent canonical AR signaling (i.e., abiraterone and enzalutamide) is growing exponentially." (PMID 26566796, 2015). "In prostate cancer, combined treatment with AR inhibitors and chemotherapeutic agents has been tested in the clinic, but the efficacy of targeting multiple pathways mis-regulated in advanced prostate cancer has not been well studied." (PMID 26509262, 2015). "The relevance of steroid hormone receptors in cancer is very well reflected by estrogen and progesterone receptors in breast cancer, and by AR in prostate cancer." (PMID 25973397, 2015).
prostate carcinoma (continued). "AR chromatin binding profiles found in treatment-resistant prostate tumors were also observed in prostate cancer cell lines, and highlighted genes correlated with survival." (PMID 26412853, 2015). "Instead, in prostate cancer cells, AR was shown to function as a co-activator of ELK1 via bypassing the classical mechanism of ELK1 activation by phosphorylation." (PMID 26342199, 2015). "Our study indicates that catalytic Topo II inhibitors can block both the transcriptional activity of AR and prostate cancer cell mitosis." (PMID 26009876, 2015). "Reduced expression of miR-190a was inversely correlated to AR levels of prostate cancer patients, and patients with higher miR-190a expression in their tumor have improved tumor-free survival." (PMID 26314494, 2015). "Consistent with these, in a tissue reconstitution model, lentiviral overexpression of ERG (or ETV1) in prostate cells collaborates with activation of the PI3K pathway or the androgen receptor (AR) pathway to induce distinct prostate carcinomas." (PMID 25780911, 2015). "In a recent report, TRPM8-promoted hypoxic tumor growth in AR+ prostate carcinoma cells involves RACK1 binding to HIF-1α and RACK1-mediated ubiquitination of HIF-1α." (PMID 26512697, 2015). "In prostate cancer, cyclin D1 has been shown to function as a corepressor to androgen receptor (AR) 18–20." (PMID 26129688, 2015). "Both steroid receptors (ERs and AR) play crucial roles in the development and progression of prostate cancer." (PMID 25569640, 2015). "Identification of PABPC1 as a co-factor of the AR provides a potential link between AR activity and active translation in prostate cancer cells." (PMID 26176602, 2015). "The downstream signals of RUNX1 in AR-negative prostate cancer cells require investigation to understand the specific role of RUNX1 in growth inhibition in AR-independent prostate cancer." (PMID 25537508, 2015). "The data presented here compares the effect of TCDD exposure on AhR and AR activity in androgen sensitive LNCaP cells versus castration resistant C4-2 prostate cancer cells." (PMID 26154658, 2015). "Targeting AR with celastrol in the presence of miR-101 would be in favor of the inhibition on cell proliferation in prostate cancer cells." (PMID 26473737, 2015). "To determine the functional significance of miR-190a in regulating the growth of AR-positive prostate cancer cells, we conducted MTT and colony formation assays." (PMID 26314494, 2015). "Specifically, evaluations of endogenous, overexpressed or silenced levels of AR expression in prostate cancer cells revealed that low AR content was required for androgen-induced EMT." (PMID 25821081, 2015). "A strong overlap of the identified eight FAIRE-seq peaks was found with known players in prostate cancer including AR, FOXA1, ERG, bromodomains BRD2 and BRD3 and, interestingly, MYC." (PMID 26412853, 2015). "Targeting AR axis is a standard strategy for prostate cancer treatment; however, the role of AR in autophagic processes is still not fully understood." (PMID 26473737, 2015). "Metastatic prostate cancer (PCa) patients are treated with androgen deprivation therapies (ADT) to deplete systemic androgen levels and inhibit androgen binding to the androgen receptor (AR) protein in prostate cancer (PCa) cells." (PMID 26036626, 2015). "Initial evidence supporting this possibility comes from our study where we show LMTK2 and AR to be binding partners in prostate cancer cells." (PMID 26008968, 2015). "AR promotes radioresistance of prostate cancers using androgen dependent or androgen independent but TK dependent mechanisms." (PMID 26546517, 2015). "High GATA2 expression predicts poor outcome in prostate cancer patients and further promotes the concept of therapeutically targeting the AR transcriptional complex in CRPC patients." (PMID 25896606, 2015).
prostate carcinoma (continued). "Dihydrotestosterone (DHT) administration inhibits SHH in prostate cancer cell lines while administration of cyclopamine modulates the activity of the androgen receptor and can attenuate cell proliferation and AR signaling induced by dihydrotestosterone." (PMID 26426053, 2015). "Prostate cancer (PC) cells depend on steroid hormones and AR to mediate oncogenic growth, and therefore, one of the key treatments for prostate cancer following surgery and radiation therapy is androgen deprivation therapy (ADT)." (PMID 26401447, 2015). "We illustrate that prognostic biomarkers for the survival of patients with prostate cancer can be identified through the assessment of AR/chromatin interaction landscapes in tumor samples." (PMID 26412853, 2015). "Other reports further emphasized the role of p21WAF/CIP1 as a direct AR target gene, in that its expression correlates with androgen stimulation and mitogenic proliferation in prostate cancer." (PMID 26622945, 2015). "This study revealed a novel mechanism by which miR-190a regulates AR signaling through targeting YB-1 in the development of prostate cancer." (PMID 26314494, 2015). "miR-185 suppresses proliferation, invasion and migration of human prostate cancer cells through targeting AR21, while the miR-124 targets AR and inhibits proliferation of prostate cancer cells." (PMID 26314494, 2015). "Western blot analysis showed that PABPC1 is expressed in all the tested cells with slightly higher expression in AR-positive prostate cancer cells." (PMID 26176602, 2015). "Currently, a lot of evidence demonstrated that the development of prostate cancer is closely related with the AR pathway, but the exact mechanism is unclear." (PMID 26491675, 2015). "Afterwards, miR-634 has been identified as a miRNA able to regulate the expression of the androgen receptor (AR) in prostate cancer cells." (PMID 26576679, 2015). "Flufenamic acid functions upstream of the androgen receptor to inhibit AR gene expression and through this function has been used as a therapeutic agent for prostate cancer." (PMID 25658610, 2015). "Aberrant activation of AR by p52 has been suggested as a mechanism of growth of human prostate cancer cells and resistance to enzalutamide under the castration condition." (PMID 26622945, 2015). "We have recently identified a role for the enhancer of split transcription factor HES6 in prostate cancer and AR signalling." (PMID 25560400, 2015). "Androgen receptor (AR) plays a pivotal role in prostate cancer development and progression, by mediating transcription of pro-mitotic genes, including UBE2C and cyclin D, resulting in prostate cancer cell proliferation." (PMID 26412853, 2015). "Androgen receptor (AR)-mediated gene expression contributes to the progression of prostate cancer (PCa), and, for patients with advanced PCa, standard treatments block AR signaling through androgen deprivation or by use of classic AR antagonists." (PMID 26207810, 2015). "Since castration was described as effective therapy for prostate cancer seven decades ago, few therapies for prostate cancer have found targets beyond AR." (PMID 26258074, 2015). "The androgen receptor is a key transcription factor contributing to the development of all stages of prostate cancer (PCa)." (PMID 25869206, 2015). "Although the mechanisms involved in regulating AR activity are poorly understood, it is essential to define this molecular event to better comprehend prostate cancer progression." (PMID 26110379, 2015). "Several other receptors play a role in the progression of cancers, especially the estrogen (ER) and androgen receptors (AR) which are seen in breast and prostate cancers." (PMID 25883673, 2015). "Patients with high PSA levels (>20) had a lower miR-190a expression, suggesting an inverse correlation between miR-190a and AR in clinical prostate cancer specimens." (PMID 26314494, 2015).